ACKR3 (atypical chemokine receptor 3)
Diseases named in the same sentence as ACKR3 in open-access papers (continued):
Sharing a sentence is not in itself a finding about the gene and the disease.
atherosclerosis (24 papers, 2014 to 2025). A disease characterized by the build-up of fatty material and calcium deposition in the arterial wall resulting in partial or complete occlusion of the arterial lumen. "We show for the first time that arterial endothelial deficiency of ACKR3 attenuates atherosclerosis as a result of diminished arterial adhesion as well as invasion of immune cells." (PMID 35674847, 2022). "Ackr3 has been shown to be involved in the trans-endothelial migration of immune cells, enabling arterial invasion and accumulation of immune cells in lesions, causing atherosclerosis, and is upregulated with aging." (PMID 39026350, 2024). "Hence, EC-specific loss of ACKR3 clearly protects against atherosclerosis under hyperlipidemic conditions." (PMID 35674847, 2022). "In our study, we observed notable transcriptional changes in endothelial cells beyond the down-regulation of atherosclerosis-inducing, pro-inflammatory genes such as Ackr3." (PMID 41082647, 2025). "Endothelial cell receptors such as C-X-C chemokine receptor type 4 (CXCR4) and atypical chemokine receptor 3 (ACKR3) can be introduced as new targets for the treatment of atherosclerosis." (PMID 37686238, 2023). "To study the role of vascular ACKR3 in atherosclerosis we crossbred Ackr3fl/fl mice with BmxCreERT2 (arterial EC specific) and SmmhcCreERT2 (SMC specific) expressing mice." (PMID 35674847, 2022). "Nevertheless, gathering evidence on the therapeutic implication of ACKR3/CXCR7 in atherosclerosis, myocardial infarction, pulmonary fibrosis, hepatic regeneration, its role in platelet pathophysiology and CAD cannot be overlooked." (PMID 35053329, 2022). "Various pharmacological tools targeting ACKR3 have been tested in murine model of atherosclerosis, myocardial infarction, stroke and different knockout murine models for ACKR3 have been developed to highlight its role crucial in CVD." (PMID 35846294, 2022). "As vascular CXCL12 and CXCR4 were shown to significantly contribute to atherosclerosis, the aim of this study was to decipher the role of arterial ACKR3 in atherosclerosis, which is an important missing link in this chemokine-axis." (PMID 35674847, 2022). "In conclusion, endothelial-ACKR3 is a novel driver of atherosclerosis and a potential future therapeutic target." (PMID 35674847, 2022). "Collectively, our findings indicate that arterial endothelial ACKR3 fuels atherosclerosis by mediating endothelium-immune cell adhesion, most likely through inflammatory MAPK and NF-kB pathways." (PMID 35674847, 2022). "We further evaluate the role of ACKR3 in the hematopoietic compartment due to the importance of the contribution of immune cells to atherosclerosis as well as the important regulatory roles of CXCL12 in the hematopoietic cell compartment." (PMID 35674847, 2022). "ACKR3/CXCR7 is richly expressed at the macrophage-enriched aortic atheroma of atherosclerosis-prone apoe−/− mice, and its expression is induced during human monocyte to macrophage differentiation in vitro." (PMID 35053329, 2022). "Activation of ACKR3 by TC14012 in ApoE-/- mice fed a high-fat diet was also reported to limit atherosclerosis initiation by promoting endothelial repair and reducing atherosclerotic lesions through inhibition of pyroptosis signaling pathways." (PMID 35846294, 2022). "Recently, ACKR3 was reported to limit atherosclerosis initiation by modulating the pyroptosis pathway, which is a highly inflammatory lytic form of apoptosis." (PMID 34494495, 2021). "The modulatory and regulatory functional spectrum of CXCL12/CXCR4/ACKR3 axis in atherosclerosis spans from proatherogenic, prothrombotic and proinflammatory to atheroprotective, plaque stabilizer and dyslipidemia rectifier." (PMID 34494495, 2021). "Showing the predominant effect of CXCL12/CXCR4/ACKR3 axis in different cells involved in atherosclerosis." (PMID 34494495, 2021).
atherosclerosis (continued). "Altogether, these findings suggest that ACKR3 promotes atherosclerosis by supporting monocyte and macrophage driven inflammatory processes." (PMID 31191301, 2019). "Recently, also a role for ACKR3 in atherosclerosis development has been described, showing that activation of ACKR3 by a synthetic ligand reduced lesion formation and ameliorated hyperlipidemia." (PMID 26257740, 2015). "However, the role of the CXCL12/CXCR4/ACKR3 axis in atherosclerosis includes a large range of cell-type-specific biological effects." (PMID 40986007, 2025). "However, the role of arterial ACKR3 in atherosclerosis is still unclear and therefore remains as a big gap in cardiovascular research." (PMID 35674847, 2022). "Future investigations are needed to understand whether the regulation of ACKR3 expression during this differentiation processes could contribute to the progression of atherosclerosis." (PMID 35846294, 2022). "Therefore, ACKR3 seems to play a role in the amelioration of atherosclerosis, since excessive cholesterol levels and hyperlipidemia are known drivers of atherosclerosis." (PMID 34501271, 2021). "Specific temporal and spatial modulators of CXCL12, CXCR4, and ACKR3, in addition to specific modulators of downstream signalling, should be explored to suppress their unwanted action in the pathogenesis of atherosclerosis and to enhance their desirable effects." (PMID 34494495, 2021). "On the other hand, there is also a possibility that these findings may differ based on the disease model; ACKR3 has been extensively studied in cancer models, whereas our study investigates a cell-specific knockout in the context of atherosclerosis under hyperlipidemic conditions." (PMID 35674847, 2022). "Moreover, endothelial Ackr3 deletion in mice also exacerbated neointimal hyperplasia following endothelial denudation injury, impaired re-endothelialization and promoted the development of atherosclerosis." (PMID 35846294, 2022). "To this end, we generated mice that lack Ackr3 specifically in arterial endothelial cells, smooth muscle cells (SMC) or in the hematopoietic compartment on an Apoe−/− background and investigated atherosclerosis development by western diet (WD) feeding." (PMID 35674847, 2022). "Chemokine receptor CXCR4 and the atypical chemokine receptor ACKR3 (formerly CXCR7) regulate essential processes in normal physiology and numerous diseases, including cancer, atherosclerosis, neurodegeneration, and autoimmunity." (PMID 35681470, 2022). "CXCL12 is a member of the chemokine family exerting a myriad role in atherosclerosis through its classical CXCR4 and atypical ACKR3 (CXCR7) receptors." (PMID 34494495, 2021). "The CXCL12/CXCR4/ACKR3 axis performs distinct functions in the pathophysiology of atherosclerosis, ranging from atheroprotective to proatherogenic functions across various cell types, through its receptors CXCR4 and ACKR3." (PMID 34494495, 2021). "For example, MZ and FO B cells display distinct roles in murine vs. human atherosclerosis, and murine MZ B cells rely strongly on ACKR3 for positioning and maturation, a dependency not yet confirmed in humans." (PMID 40986007, 2025). "In particular, ACKR3’s role in regulating CXCL12 bioavailability and modulating CXCR4-mediated chemotaxis positions it as an intriguing target to fine-tune B-cell activity in atherosclerosis." (PMID 40986007, 2025). "Although direct evidence in atherosclerosis is currently lacking, ACKR3’s expression pattern and gradient-modulating capacity make it a plausible regulator of B-cell trafficking and antibody output in cardiovascular inflammation." (PMID 40986007, 2025). "However, ACKR3 and SELE drive atherosclerosis by promoting immune cell adhesion to the vascular endothelium." (PMID 37491214, 2023). "Lack of smooth muscle cell-specific as well as hematopoietic ACKR3 did not impact atherosclerosis in mice." (PMID 35674847, 2022).
atherosclerosis (continued). "Nonetheless, this role of ACKR3 has never been shown in vascular endothelium in vivo before, especially in the context of atherosclerosis." (PMID 35674847, 2022). "We studied the role of arterial ACKR3 in atherosclerosis using western diet-fed Apoe−/− mice lacking Ackr3 in arterial endothelial as well as smooth muscle cells." (PMID 35674847, 2022). "However, this review focuses specifically on the role of CXCR4 and CXCR7 (ACKR3) receptors, their complex mutual relationship and their interaction with the ligand CXCL12 (SDF-1) in atherosclerosis." (PMID 34494495, 2021). "Deletion of ACKR3/CXCR7 in apoE−/− mice results in increased atherosclerotic lesion formation and the application of a small molecule ACK3 agonist decreases atherosclerosis by a mechanism that relates to the expression of ACK3 in white adipose tissue, where it takes part in cholesterol metabolism." (PMID 25152735, 2014). "However, it is also speculated that ACKR3-mediated EPC adhesion may eventually lead to trans-endothelial leukocyte adhesion and migration, contributing to atherosclerosis." (PMID 34494495, 2021).
glioblastoma (22 papers, 2013 to 2024). The most malignant astrocytic tumor (WHO grade IV). "Cx43 and ACKR3 are co-expressed in mouse brain astrocytes and human glioblastoma cells and form a complex in embryonic mouse brain." (PMID 32978390, 2020). "In cancer, ACKR3 was found expressed on many tumor cells (such as renal carcinoma, breast cancer, and glioblastoma) and by tumoral ECs." (PMID 30894861, 2019). "In a glioblastoma murine model, mice treated with X7Ab against ACKR3 in combination with Temozolomide (TMZ) showed significant tumor reduction and longer survival, enhancing M1 macrophage activation." (PMID 30894861, 2019). "CXCR4 and ACKR3 in glioblastoma are found on tumour cells, GAMs and endothelial cells." (PMID 33803414, 2021). "Despite ACKR3 being recognised as a CXCL12 scavenging receptor, the functional role of ACKR3 in glioblastoma is complex because it might regulate CXCL12 levels in the TME and concomitantly modulate CXCR4 signalling." (PMID 33803414, 2021). "Double immunostaining of Cx43 and either ACKR3 or CXCR4 in two patient-derived glioblastoma-initiating cell lines with endogenous expression of the three proteins further indicated that a higher fraction of Cx43 is co-localized with ACKR3, in comparison with CXCR4." (PMID 32978390, 2020). "In fact, it could be shown experimentally that all components of the CXCL12/CXCR4/ACKR3 axis are relevant for recurrence of glioblastoma after radiotherapy, as inhibition of ACKR3 alone in combination with irradiation was also effective in preclinical models." (PMID 30813533, 2019). "Moreover, using complementary approaches, we showed that Cx43 interacts with ACKR3 but not with the functionally related CXCR4 in both HEK293T cells and glioblastoma-initiating cell lines." (PMID 32978390, 2020).
pancreatic cancer (20 papers, 2009 to 2024). "In conclusion, data show that CXCL12/CXCR4/ACKR3 axis is involved in keeping the communication between pancreatic cancer and its microenvironment." (PMID 31275385, 2019). "Interestingly, the administration of CXCL12 in pancreatic cancer cells showed also the activation of signaling pathways mediated by ACKR3, which, therefore, has not only a scavenger role for CXCL12." (PMID 31275385, 2019). "Moreover, 73% of human pancreatic cancer tissues express both CXCR4 and ACKR3." (PMID 31275385, 2019).
melanoma (18 papers, 2014 to 2025). A malignant, usually aggressive tumor composed of atypical, neoplastic melanocytes. "Melanoma cell expressed Mif signaled to rCap and venous ECs through Ackr3 (a.k.a CXCR7) receptor, which has been shown to mediate inflammatory cell interactions with ECs via adhesion molecule expression." (PMID 39627185, 2024). "EVs derived from osteotropic LCP melanoma cells appear to stimulate the osteotropic behavior of SK-Mel28 and WM-266, non-osteotropic tumor cells, toward bone in a CXCL12-stimulated manner through the atypical chemokine receptor 3 (ACKR3)/CXCR4 axis." (PMID 39698539, 2024).
hepatocellular carcinoma (17 papers, 2010 to 2024). A malignant tumor that arises from hepatocytes. "utilized bioinformatics and network pharmacology to identify that the regulator of cell cycle gene (RGCC) and atypical chemokine receptor 3 (ACKR3) are implicated in the progression from non-alcoholic liver disease to hepatocellular carcinoma and impact the prognosis of hepatocellular carcinoma." (PMID 39206194, 2024).
ovarian carcinoma (16 papers, 2013 to 2025). A malignant neoplasm originating from the surface ovarian epithelium. "Oncoprint profile of CYCS, VEGFA, IL6, UQCRC1, UQCRFS1, COX5B, ACKR3/CXCR7, and FYN indicated that these genes were either amplified or overexpressed in 4–25% of the ovarian cancer patients." (PMID 34439877, 2021). "The identification of CYCS, VEGFA, IL6, UQCRC1, UQCRFS1, COX5B, ACKR3/CXCR7, and FYN as pro-tumorigenic nodes designates them as the novel and potentially druggable targets for effective targeted adjuvant therapy for ovarian cancer." (PMID 34439877, 2021).
myocardial infarction (14 papers, 2015 to 2025). Gross necrosis of the myocardium, as a result of interruption of the blood supply to the area, as in coronary thrombosis. "Recently, the importance of ACKR3 expression in endothelial cells has been shown to be critical for vascular homeostasis and cardiac remodeling after myocardial infarction in mice." (PMID 35383158, 2022). "Platelet surface expression of ACKR3/CXCR7 is significantly enhanced following myocardial infarction (MI) in acute coronary syndrome (ACS) patients, and is also associated with improved functional recovery and prognosis." (PMID 35053329, 2022). "In contrast, another study demonstrated a protective role of ACKR3, albeit in normolipidemic myocardial infarction and endothelial denudation injury mouse models, and reported that the loss of endothelial ACKR3 increased neointimal hyperplasia." (PMID 34494495, 2021). "Conditional endothelial ACKR3 deletion promoted neointimal formation after endothelial injury and exacerbated heart functional impairment after myocardial infarction (MI)." (PMID 33374806, 2020).
autoimmune disease (12 papers, 2019 to 2025). A disorder resulting from loss of function or tissue destruction of an organ or multiple organs, arising from humoral or cellular immune responses of the individual to their own tissue constituents. "ACKR3 is an atypical chemokine receptor associated with some autoimmune diseases and inflammatory responses, and the CXCL12/CXCR4/ACKR3 axis is a potential therapeutic target for several inflammatory diseases." (PMID 36118358, 2022). "Similar to CXCR4, ACKR3 is implicated in some autoimmune diseases, such as rheumatoid arthritis, inflammatory bowel disease, and experimental autoimmune encephalomyelitis (EAE)." (PMID 31507535, 2019). "The atypical chemokine receptor 3 (ACKR3) has emerged as a promising drug target for the treatment of cancer, cardiovascular, and autoimmune diseases." (PMID 41317408, 2025). "The chemokine CXCL12 and its two cognate receptors—CXCR4 and ACKR3—are key players in various homeostatic and pathophysiological processes, including embryonic development, autoimmune diseases, tissue repair, and cancer." (PMID 39662834, 2024). "The CXCL12/ACKR3 axis has been previously recognized to play a crucial role in various autoimmune diseases." (PMID 39215271, 2024). "Previous studies have reported that ACKR3, known as C-X-C chemokine receptor 7, is related to the function of myeloid lineage, and autoimmune diseases." (PMID 35011190, 2021). "The present review discusses the role of the CXCL12/CXCR4/ACKR3 axis in inflammation, focusing on its involvement in several autoimmune diseases." (PMID 31507535, 2019). "Here, we review the involvement of the CXCL12/CXCR4/ACKR3 axis in some of the most prevalent autoimmune diseases: psoriasis, multiple sclerosis, rheumatoid arthritis, lupus, type I diabetes (T1D), and inflammatory bowel disease." (PMID 31507535, 2019).
lymphoma (12 papers, 2014 to 2025). A malignant (clonal) proliferation of B- lymphocytes or T- lymphocytes which involves the lymph nodes, bone marrow and/or extranodal sites. "Hence, like in vitro, also in vivo wild type lymphoma cells appeared to promote the migration of ACKR3 deficient VAL-ko." (PMID 36713377, 2022). "Similarly, in the localized xenograft model ACKR3 expression correlated with invasion of draining lymph nodes, underlining the role of ACKR3 for cell mobility and aggressiveness of lymphoma." (PMID 29156704, 2017). "This further demonstrated that ACKR3 enhances CXCL12/CXCR4-mediated intercellular-induced lymphoma migration by promoting LTB4 production, revealing the cell-to-cell-induced migration of lymphoma." (PMID 40427609, 2025). "We demonstrate here that CXCR4-mediated migration of lymphoma cells towards CXCL12 requires the expression of functional ACKR3 at the cell surface." (PMID 36713377, 2022). "Here, functional expression of ACKR3 in DLBCL cells was necessary for colonization of the draining lymph node in an in vivo subcutaneous lymphoma model." (PMID 29156704, 2017). "The inhibition of ACKR3 expression via pharmacological or molecular genetic techniques could impair the migration of lymphoma cells toward CXCL12 and significantly reduce chemotaxis to CXCL12." (PMID 40427609, 2025). "Interfering with this axis by ACKR3 deletion impairs lymphoma cell migration towards CXCL12." (PMID 36713377, 2022). "Moreover, in a disseminated in vivo lymphoma model, ACKR3 expression was required for bone marrow and brain invasion and local tumor growth." (PMID 29156704, 2017). "Antagonizing scavenging activity of ACKR3 with small molecules or genetic deletion may interfere with the formation of local CXCL12 cues attenuating lymphoma cell dissemination." (PMID 29156704, 2017). "In addition, the CXCL12/ACKR3/CXCR4 axis was proposed to be involved in lymphoma." (PMID 36713377, 2022). "Genetic ablation of ACKR3 by CRISPR/Cas9 attenuates cell migration in vivo and markedly limits tissues invasion of the lymphoma cells." (PMID 29156704, 2017). "This approach, first validated in transfected cells by detecting the presence of CXCR4 and ACKR3 homo-oligomers and hetero-oligomers, reveals for the first time endogenous CXCR4 homo-oligomers in non-transfected human leukemia/lymphoma-derived cancer cell lines." (PMID 41402431, 2025).
breast tumor (10 papers, 2012 to 2023). "On one hand, it was found that the expression of CXCR7/ACKR3 by breast tumor cells has provided growth advantages to luminal breast tumor cells (at times even when CXCR4 was not active in this respect), and reduced trail-mediated apoptosis in such cells." (PMID 32582148, 2020). "However, another study demonstrated different roles for CXCR4 and CXCR7/ACKR3 in regulating estrogen-dependent growth of luminal breast tumor cells, where CXCR4 enhanced cancer cell growth and CXCR7/ACKR3 over-expression inhibited cell proliferation, possibly through CXCL12 sequestration." (PMID 32582148, 2020). "Additional research in this direction provided evidence to complex roles for CXCR7/ACKR3 and for its interactions with CXCR4 in regulating the proliferation and growth of breast tumor cells." (PMID 32582148, 2020).
coronary artery disease (10 papers, 2016 to 2025). "Recently, it has been shown that patients suffering from coronary artery disease with elevated ACKR3 levels had an improved clinical prognosis and platelets showed less aggregation." (PMID 39373210, 2025). "Enhanced platelet expression of the chemokine receptor ACKR3/CXCR7 has been reported in coronary artery disease patients with reduced platelet aggregation." (PMID 36238558, 2022).